SOX18 (SRY-box transcription factor 18)
Description:
Transcriptional activator that binds to the consensus sequence 5'-AACAAAG-3' in the promoter of target genes and plays an essential role in embryonic cardiovascular development and lymphangiogenesis. Activates transcription of PROX1 and other genes coding for lymphatic endothelial markers. Plays an essential role in triggering the differentiation of lymph vessels, but is not required for the maintenance of differentiated lymphatic endothelial cells. Plays an important role in postnatal angiogenesis, where it is functionally redundant with SOX17. Interaction with MEF2C enhances transcriptional activation. Besides, required for normal hair development.
Synonyms: HLTRS; HLTS
Tractability: PROTAC: a small molecule that binds it is known.
Target class: Transcription factor
Gene: Protein-coding gene on chromosome 20 (64,047,582 to 64,049,639, reverse strand). Ensembl gene ENSG00000203883.
Subcellular location: Nucleus
Subcellular location (Human Protein Atlas): Nucleoplasm
Gene Ontology:
Molecular function: DNA-binding transcription activator activity, RNA polymerase II-specific; RNA polymerase II cis-regulatory region sequence-specific DNA binding; sequence-specific double-stranded DNA binding; transcription cis-regulatory region binding; DNA-binding transcription factor activity, RNA polymerase II-specific; DNA binding; DNA-binding transcription factor activity; sequence-specific DNA binding
Biological process: angiogenesis; blood vessel endothelial cell migration; establishment of endothelial barrier; hair cycle process; lymphangiogenesis; negative regulation of transcription by RNA polymerase II; positive regulation of transcription by RNA polymerase II; embryonic heart tube development; endocardial cell differentiation; endocardium formation; heart looping; lymphatic endothelial cell differentiation; negative regulation of DNA-templated transcription; outflow tract morphogenesis; positive regulation of DNA-templated transcription; vasculature development; vasculogenesis; anatomical structure formation involved in morphogenesis; tissue development
Cellular component: chromatin; nucleus; transcription regulator complex
Genetic constraint (gnomAD): Loss-of-function variants: 2 observed, 4.04 expected, observed/expected ratio (o/e) 0.49, 90% interval 0.2 to 1.48. That is too few expected variants to judge how well the gene tolerates losing a copy. Missense variants: 540 observed, 388.46 expected, observed/expected ratio (o/e) 1.39, 90% interval 1.29 to 1.49. Synonymous variants: 291 observed, 191.73 expected, observed/expected ratio (o/e) 1.52, 90% interval 1.38 to 1.67.
Homologues: Orthologues: chimpanzee SOX18 (99% identical), macaque SOX18 (99% identical), pig SOX18 (93% identical), guinea pig SOX18 (89% identical), dog SOX18 (87% identical), mouse Sox18 (86% identical), rat Sox18 (86% identical), tropical clawed frog sox18 (50% identical), Drosophila melanogaster Sox14 (24% identical), Drosophila melanogaster Sox21a (19% identical), Drosophila melanogaster Sox102F (18% identical), Caenorhabditis elegans sox-4 (14% identical), and 1 more. Paralogues in human: SOX17 (41% identical), SOX7 (39% identical), SOX9 (24% identical), SOX8 (22% identical), SOX10 (22% identical), CFAP65 (22% identical), SOX1 (22% identical), SOX2 (21% identical), SOX3 (21% identical), SOX11 (21% identical), SOX13 (21% identical), SOX5 (21% identical), and 8 more.
Diseases named in the same sentence as SOX18 in open-access papers:
SOX18 is named in the same sentence as 80 diseases in open-access papers, as found by Europe PMC text mining. Sharing a sentence is not in itself a finding about the gene and the disease. The quoted sentences say what the papers report.
lymphedema (15 papers, 2007 to 2025). Excess fluid collection in tissues, causing swelling. "Previous evidence described the genetic screening of hereditary syndromes accompanied by the genetic mutations in genes such as FOXC2, FLT-4, and SOX18 for lymphedema-distichiasis, Milroy disease, and hypotrichosis-lymphedema-telangiectasia, respectively." (PMID 37267206, 2023). "Several genes specifically have been associated with named lymphatic diseases, such as SOX18 in hypotrichosis-lymphedema-telangiectasia, FOXC2 in lymphedema-distichiasis, and VEGFR3 in Nonne–Milroy disease." (PMID 35743063, 2022). "A study on human patients and their offspring identified a recessive mutation in SOX18 that played a key role in the development of hair, blood vessels, and lymphatic vessels, and was mainly manifested clinically as sparse hair-lymphedema-telangiectasia." (PMID 34946875, 2021). "For example, Sox18 and Foxc2 mutations in humans cause hypotrichosis-lymphoedema-telangiectasia and lymphedema-distichiasis, respectively." (PMID 32882780, 2021). "Mutation of human SOX18 is associated with hypotrichosis–lymphedema–telangiectasia (OMIM 607823), which is characterized by lower-limb lymphedema, cutaneous telangiectasia, and dilatation of superficial vessels." (PMID 31908356, 2020). "Primary lymphedema can be an indicator of various complex hereditary syndromes, such as Noonan syndrome (associated with the PTPN11 gene), lymphedema–distichiasis syndrome (FOXC2), and hypotrichosis–lymphedema–telangiectasia syndrome (SOX18)." (PMID 38791500, 2024). "In particular, mutations in SOX18, PROX1, GATA2, and FOXC2 cause various forms of syndromic lymphedema." (PMID 35806420, 2022). "Lymphedema-distichiasis is linked to the forkhead transrciption factor FOXC2, and the lymphedema-hypotrichosis-telangiectasia syndrome is caused by mutations in the transcription factor SOX18." (PMID 17584927, 2007). "Notably, variations in the SOX18 gene have previously been involved in hypotrichosis–lymphedema–telangiectasia syndrome as well as aortic dilation, pulmonary hypertension, dysmorphic face, renal failure, hydrocele, chylothorax, dysplastic nails, and cutis marmorata in humans." (PMID 36010266, 2022). "Similarly, mutations in SOX18 have been linked to hypotrichosis–lymphedema–telangiectasia but to date no change in SOX18 expression has been associated with blood disorders." (PMID 27411892, 2016). "Genetic predisposition of lymphatic dysfunction results in primary lymphedema such as genes pertaining to lymphagiogenesis (VEGFR3, FOXC2, SOX18, ITGA9 and etc.)are the influencing factor of primary lymphedema in defective form." (PMID 37986071, 2023). "Mutations associated with the VEGF-C/VEGR3 signaling pathway, including changes in FOXC2, as well as key transcription factors involved in LEC specification, such as Sox-18 and GATA2, contribute to the development of primary lymphedema." (PMID 32510325, 2020). "TIMP3 mutations cause Sorby's fundus dystrophy, a disease, where choroidal vessel integrity is affected; SOX18 inactivation leads to lymphedema-distichiasis syndrome, with clinical signs of edema and abnormal morphology of capillaries and arterioles and FLT4 mutations cause Nonne-Milroy lymphedema." (PMID 19924294, 2009).
breast cancer (12 papers, 2011 to 2025). A primary or metastatic malignant neoplasm involving the breast. "This lymphatic response to Sm4-treatment is consistent with that of SOX18 loss of function during lymphatic spread of solid cancers Together, this demonstrates that Sm4 improved the outcome of induced breast cancer by interfering with tumor-induced neo-vascularization and associated metastasis." (PMID 28137359, 2017). "Blockade of SOX18‐dependent interactions, on the other hand, reduced the tumour vascular density and potently suppressed tumour metastasis of melanomas and breast cancer." (PMID 39231761, 2025). "The in vitro transfection of MCF-7 BC cell lines with siRNA against SOX18 inhibited cell proliferation and invasion and promoted apoptosis in breast cancer cells via the suppression of the Ras-dependent pathway." (PMID 39795985, 2024). "Inhibition of SOX18 expression in the breast cancer cell line MCF-7 leads to a decrease in the proliferative and migratory abilities of this cell line due to the destabilization of the actin cytoskeleton." (PMID 33152990, 2020). "Our results provide a proof of concept that targeting the transcription factor SOX18 with Sm4 is an effective molecular strategy to interfere with the metastatic spread in a pre-clinical model of breast cancer." (PMID 28137359, 2017). "We compared the expression levels of SOX7 and other co-expressed genes in the Wnt/β-catenin pathway and found that the expression of SOX7, SOX17 and SOX18 was all reduced significantly in the breast cancer tissues compared to normal controls." (PMID 27188720, 2016). "We found that the expression levels of SOX7, SOX17 and SOX18 were reduced significantly in breast cancer tissues compared to normal controls." (PMID 27188720, 2016). "Several studies have reported the overexpression of SOX18 in gastric, ovarian, non-small cell lung and breast cancer." (PMID 26151573, 2015). "Additionally, suppressing SOX18 via an siRNA has been correlated with impaired cell growth in breast cancer and hepatocellular carcinoma cells." (PMID 36620216, 2022). "In breast cancer, SOX18 correlates with the degree of malignancy and the proliferation status." (PMID 33152990, 2020). "SOX18 gene expression has been observed in a number of human cell lines, such as, for example, in the cells of germ-cell tumors and in gastric, pancreatic and breast cancers." (PMID 33152990, 2020). "In breast cancer, there is a positive correlation between SOX18 and vascular endothelial growth factor D (VEGF-D), suggesting that SOX18 positively influences angiogenesis." (PMID 38132479, 2023). "Firstly, using gene expression files, we found that the expression of SOX7, SOX17 and SOX18 was significantly reduced, whereas SOX4 was markedly increased in breast cancer tissues compared to normal tissues." (PMID 27188720, 2016). "Previous studies have suggested the promoting effect of SOX18 on cell proliferation of vascular smooth muscle cells and MCF-7 breast cancer cells." (PMID 26151573, 2015). "Besides MYC itself, we find upregulation of other breast cancer stem cell factors (SOX2, SOX18, THY1, EYA1, GLI2, SALL1, GLIS1, CXCR4), suggesting that MYC HME cells adopt a stem-like state." (PMID 31942031, 2020). "Recent studies reported that the overexpression of SOX18 was found in various types of tumors such as breast cancer, non-small cell lung cancer, prostate cancer, and non-melanoma skin cancer, and its expression correlates with cell proliferation, migration, and invasion of tumor cells." (PMID 31189744, 2019).
hypotrichosis (11 papers, 2010 to 2024). A congenital condition, usually due to genetic aberrations, that is characterized by a lack of hair growth on the head and/or body. "Recessive and dominant mutations in SOX18 in humans are known to cause hypotrichosis-lymphedema-telangiectasia syndrome with a combination of hair and cardiovascular anomalies, including symptoms of lymphatic dysfunction." (PMID 27757173, 2016). "At present, the only SoxF family member that is unequivocally implicated in human disease is Sox18, which is mutated in the hereditary syndrome hypotrichosis-lymphedema-telangiectasia (HLT)." (PMID 26630461, 2015). "Among the other genes with known functions in the deletion region is SRY-box 18 (SOX18), homozygous missense mutations and heterozygous nonsense mutations of which have been associated with recessive and dominant forms of hypotrichosis-lymphedema-telangiectasia syndrome." (PMID 20805988, 2010).
hemangioma (7 papers, 2019 to 2025). A benign vascular lesion characterized by the formation of capillary-sized or cavernous vascular channels. "Of note the S(-) enantiomer was also active at disrupting corneal vessel outgrowth, suggesting that conformational changes that occur in the SOX18 mutated protein may attenuate the discrepancy in enantiomeric activities previously observed in the hemangioma endothelial differentiation model." (PMID 31358114, 2019). "The efficacy of propranolol was independent of its β-AR blocker activity and was attributable to the direct targeting of the transcription factor SOX18, which, in turn, reduced hemangioma blood vessel formation." (PMID 35104803, 2022). "(A) Infantile) hemangioma tissue section stained for SOX18 (red), Ki67 (green), CD31 (orange), D2-40 (pink) and DAPI (blue) reveals the presence of SOX18 expression in a large subset of hemangioma endothelial cells (arrows)." (PMID 31358114, 2019). "Indeed, we found elevated SOX18+SREBP2+ endothelial cells in the congenital hemangioma entities RICH and NICH, suggesting that further exploration of the MVP in other vascular anomalies is warranted." (PMID 39998898, 2025). "To assess the physiological relevance of RBPJ in the context of hemangioma, we analyzed both RBPJ and SOX18 expression patterns in formalin-fixed, paraffin-embedded (FFPE) sections from patients with IH." (PMID 34874911, 2022). "Induced differentiation of hemangioma-derived stem cells (HemSC) into hemangioma endothelial cells with VEGF-B, increases SOX18 expression." (PMID 33634164, 2020). "(C) VEGF-B treatment of HemSC from four different infantile hemangiomas resulted in increased CDH5 (an endothelial cell marker), SOX18 and ADBR2 (β2 adrenergic receptor) mRNA." (PMID 31358114, 2019). "New approaches including non-beta blocker enantiomers of propranolol and atenolol (which targets the transcription factor SOX18 in hemangioma stem cells) inhibit hemangioma vessel formation in vivo without apparent side effects in mice." (PMID 37060495, 2023).
non-small cell lung carcinoma (7 papers, 2019 to 2025). A group of at least three distinct histological types of lung cancer, including non-small cell squamous cell carcinoma, adenocarcinoma, and large cell carcinoma. "Cytoplasmic SOX18 correlates with poor patient outcome in adenocarcinoma and is associated with non-small cell lung cancer progression." (PMID 33397924, 2021). "In lung cancer, the inhibition of SOX18 with a specific inhibitor called Sm4 has shown cytotoxic effects on non-small cell lung cancer (NSCLC) cell lines, leading to cell cycle disruption and up-regulation of p21, a key regulator of cell cycle progression." (PMID 39869563, 2025). "In non-small-cell lung cancer (NSCLC), the contributions of SOX18 and SOX30 remain insufficiently understood, particularly regarding their epigenetic regulation and network interactions with angiogenic and immune-modulatory pathways." (PMID 41373817, 2025). "The role of the SOX18 and SOX30 expression in non-small-cell lung cancers (NSCLCs) is not yet fully understood." (PMID 33152990, 2020). "The role of the SOX18 and SOX30 expression in non-small-cell lung cancers (NSCLCs), especially in lung adenocarcinoma (AC) and lung squamous-cell carcinoma (LSCC), is not yet fully understood." (PMID 33152990, 2020).
osteosarcoma (7 papers, 2019 to 2025). A usually aggressive malignant bone-forming mesenchymal neoplasm, predominantly affecting adolescents and young adults. "Their study demonstrated that SOX18 silencing led to an increase in p21 expression, while SOX18 overexpression decreased p21 expression in osteosarcoma cells." (PMID 37511076, 2023). "In osteosarcoma, the level of miR-655 decreased, LINC00689 can increase the expression level of SOX18 by combining with miR-655, thus promoting the osteosarcoma cell proliferation, migration and invasion." (PMID 36309693, 2022). "In contrast, SOX18 is overexpressed in osteosarcoma, and promotes cell proliferation, migration, and invasion, inhibiting cell cycle arrest and apoptosis." (PMID 34122528, 2021). "In previous studies, SOX18 silencing induced G0/G1 arrest in colorectal cancer, laryngeal, hepatocellular carcinoma, renal and blader cancer, while S-to-G2/M inhibition was observed in SOX18 knockdown osteosarcoma cells." (PMID 37511076, 2023). "Findings from this study indicate that lncRNA DUXAP10 can act as an oncogene in osteosarcoma by binding HuR to up-regulate the expression of SOX18 at a post-transcriptional level, which may provide a new target for OS clinical diagnosis and treatment." (PMID 36053455, 2022). "The expression of HERC2 and SOX18 in osteosarcoma is significantly negatively correlated and SOX18 has been tested to play a significant part in the proliferation, migration, invasion and apoptosis of osteosarcoma cells." (PMID 34820159, 2021). "Current evidence suggests that SOX18 has an oncogenic role in carcinogenesis, promoting migration, invasion, and proliferation in cell lines of various cancer origins, including bladder, breast, cervix, colon, larynx, liver, kidneys, osteosarcoma, pancreas, and prostate." (PMID 37511076, 2023). "Besides, HERC2 interacts with SOX18, which is overexpressed in osteosarcoma cells." (PMID 34820159, 2021).
hepatocellular carcinoma (6 papers, 2015 to 2025). A malignant tumor that arises from hepatocytes. "Increased expression of SOX18 has also been shown to be important for cell migration in several cancers such as cervical carcinoma, hepatocellular carcinoma." (PMID 36620216, 2022). "A study of hepatocellular carcinoma (HCC) demonstrated that SOX18 overexpression mediated infiltration of Tregs and promoted HCC progression and metastasis." (PMID 39355773, 2024). "In hepatocellular carcinoma (HCC), PRMT1 directly enhances SOX18 transcription by increasing H4R3me2a levels at its promoter, thereby promoting HCC cell proliferation." (PMID 41256732, 2025).
cervical carcinoma (5 papers, 2015 to 2025). A carcinoma arising from either the exocervical squamous epithelium or the endocervical glandular epithelium. "It was reported that Hedgehog signaling acts upstream of Sox2 in cancer stem cells, and Sox18 is a target gene of hedgehog signaling in cervical carcinoma." (PMID 32674056, 2020). "Recently it became evident that expression of SOX18 gene in tumors is not restricted to endothelium of accompanying blood and lymphatic vessels, but in tumor cells as well.In this paper we have identified human SOX18 gene as a novel target gene of Hedgehog signaling in cervical carcinoma cell lines." (PMID 26588701, 2015). "In this paper we addressed the question whether SOX18 expression is under control of this signaling pathway in cervical carcinoma cell lines." (PMID 26588701, 2015). "Therefore, we performed functional analysis studying the effect of GLI transcription factors overexpression on the activity of SOX18 promoter (represented with previously characterized SOX18construct 892pCAT6 in cervical carcinoma cells." (PMID 26588701, 2015). "Our findings link regulation of SOX18 transcription with HH signaling and its final effectors, GLI transcription factors in cervical carcinoma cell lines." (PMID 26588701, 2015). "Consistent with the findings showing activation of SOX18 before invasion, studies have shown that overexpression of SOX18 can significantly enhance the invasiveness and migration of cervical carcinoma cells, without affecting proliferative potential." (PMID 40678065, 2025). "Finally, we demonstrated that inhibition of SOX18 function, using dominant-negative approach, inhibits to some extent GLI1/GLI2-mediated migration of cervical carcinoma cells in vitro." (PMID 26588701, 2015). "In addition, we analyzed the role of SOX18 in malignant potential of cervical carcinoma cell line, and showed that its overexpression has no influence on cells proliferation and viability, but substantially promotes migration and invasion of cells in vitro." (PMID 26588701, 2015).